CRP (C-reactive protein)
Diseases named in the same sentence as CRP in open-access papers (continued):
Sharing a sentence is not in itself a finding about the gene and the disease.
pneumonia (continued). "Additional variables that were strongly associated with mortality were: male sex, pneumonia, heart failure and CRP level (for each 10 mg/l increment)." (PMID 33789578, 2021). "CRP levels above 75 mg/dL were also significantly associated with severe pneumonia at admission (OR 38.9; 95% CI 5.1–299, p = 0.0004) while CRP levels below 25 mg/dL were negatively associated with severe disease (OR 0.19; 95% CI 0.08–0.48, p = 0.0003)." (PMID 34412597, 2021). "The biological marker such as CRP has diagnostic or prognostic value in lower respiratory tract infections and pneumonia." (PMID 34447386, 2021). "White blood cell count > 20,000/μL and CRP levels > 75 mg/dL were associated with severe pneumonia at admission while congenital disease was associated with fatal outcome." (PMID 34412597, 2021). "High white cell counts (> 20,000 cells/μL) and high CRP levels (> 75 mg/dL) were associated with severe pneumonia at admission." (PMID 34412597, 2021). "Younger age, crowded housing, and lower C-reactive protein levels were predictors of severe RSV-associated pneumonia." (PMID 34306103, 2021). "White blood cell count > 20,000/μL and C-Reactive Protein > 75 mg/dL were associated with severe pneumonia at admission." (PMID 34412597, 2021). "Recently, some studies have reported that C-reactive protein (CRP) levels can be used in the early diagnosis of pneumonia and that higher CRP levels were associated with severe pneumonia." (PMID 33968148, 2021). "The univariate Cox regression revealed that CAD, congestive heart failure, TACS, pneumonia, and elevated hs-CRP level were positively associated, while hyperlipidemia was negatively associated with 30-day mortality among NS patients with IS." (PMID 34090375, 2021). "Patients with influenza-associated pneumonia showed more elevated C-reactive protein (CRP) than those with COVID-19-associated pneumonia (44.4% vs. 90.9%, p = 0.001)." (PMID 33567507, 2021). "These patients also manifest a hyper-inflammatory state or “cytokine storm” characterized by elevated levels of inflammatory markers such as the C-reactive protein (CRP) and interleukin-6 which have been linked to the severity of pneumonia and mortality." (PMID 33312811, 2020). "This study demonstrated a high use of CRP tests, and moreover, an elevated CRP level was strongly associated with being diagnosed with pneumonia." (PMID 31650886, 2020). "In the present study, doxycycline was, in divergence with guidelines, prescribed surprisingly frequently for patients with pneumonia and was associated with lower CRP levels." (PMID 32127365, 2020). "A Dutch study suggested that patients with milder LRTI symptoms and CRP <20 mg/L are at low risk for pneumonia." (PMID 33399009, 2020). "In this study, we noted that higher median values of leukocytes,neutrophils and C-reactive protein were associated with the increased severity ofCOVID-19 pneumonia, which suggests that a cytokine storm is associated with diseaseseverity." (PMID 32490680, 2020). "Admission CRP < 100 mg/L has reduced risk for 30-day mortality, need for mechanical ventilation and/or inotropic support, and complicated pneumonia." (PMID 32689999, 2020). "Even a slightly elevated CRP (≥11 mg/L) was positively associated with being diagnosed with pneumonia." (PMID 31650886, 2020). "Contrary, most patients had a CRP test performed, and even a slightly elevated CRP test (≥11 mg/L) was positively associated with being diagnosed with pneumonia." (PMID 31650886, 2020). "Previous studies have demonstrated that a combination of symptoms, signs, and CRP have high diagnostic value in detecting and mainly ruling out pneumonia." (PMID 31650886, 2020). "Five diagnostic biomarkers have been linked to the diagnosis of pneumonia, namely: C-reactive protein (CRP), Procalcitonin (PCT), a Soluble triggering receptor expressed on myeloid cells-1 (STREM-1), CD163, and High Mobility Group Box-1(HMGB-1)." (PMID 33218302, 2020).
pneumonia (continued). "There was a positive association between the degree of suspicion of pneumonia and CRP levels (p < 0.001)." (PMID 33399009, 2020). "The diagnosis of acute bronchitis was associated with a viral origin and pneumonia with bacterial, corresponding to the result of the CRP tests." (PMID 32031035, 2020). "Patients who are at intermediate risk (2,5–20%) for having pneumonia, using clinical signs and symptoms only, would benefit from CRP testing to identify the patients who have a high risk of pneumonia." (PMID 31747890, 2019). "Current evidences have shown that adding CRP value to basic signs and symptoms models in diagnosing pneumonia improved diagnostic discrimination of adult patients in primary care." (PMID 31110214, 2019). "PCT and CRP have also been studied as biomarkers for distinguishing cases of pneumonia caused by intra- and extracellular bacteria." (PMID 31183362, 2019). "As a categorical variable, a CRP value over 100 mg/l, or even over 80 mg/l, was associated with a pneumonia finding in the chest radiograph (P < .05 for both)." (PMID 30991957, 2019). "For example, high levels of CRP and procalcitonin accompanied by unilateral hyperventilation and grunting were associated with pneumonia." (PMID 29988379, 2018). "This was consistent with previous report, CRP kinetics can be used to identify ventilator-associated pneumonia patients with poor outcome." (PMID 30285748, 2018). "In a high prevalence setting (10 studies, pneumonia >10%), additional diagnostic tests such as oxygen saturation, C-reactive protein, and white blood cell count are more promising." (PMID 30367067, 2018). "Pneumonia, pleural effusions and elevated c-reactive protein post operative have been associated with increased risk of atrial fibrillation." (PMID 29921284, 2018). "Our study suggested that both PCT and CRP are helpful to acertain extent in detecting pneumonia caused by different types ofinfection." (PMID 29846409, 2018). "CRP measurement independently distinguished between pneumonia and other causes of exacerbations in another study of patients hospitalised with asthma and COPD (cut-off value of 48 mg/L with sensitivity of 91% and specificity of 93%)." (PMID 28969667, 2017). "First identified in sera from pneumonia patients in 1930 by its ability to precipitate the C-polysaccharide of Streptococcus pneumoniae, CRP has since been associated with bacterial infections generally and with noninfectious causes of inflammation." (PMID 28575375, 2017). "We also evaluate the sensitivity and specificity of elevated CRP for bacterial pneumonia in comparison to pneumonia likely caused by respiratory syncytial virus (RSV), the most common respiratory virus associated with childhood pneumonia." (PMID 28575375, 2017). "The Pneumonia Etiology Research for Child Health (PERCH) study provides an opportunity to examine the association between CRP and etiology of pneumonia in a number of children in several countries." (PMID 28575375, 2017). "Serum procalcitonin and high-sensitivity C-reactive protein (hs-CRP) elevations have been associated with pneumonia in adults." (PMID 26772604, 2016). "C-reactive protein was significantly higher in patients with pneumococcal pneumonia than in patients with pneumonia caused by other bacteria." (PMID 27326370, 2016). "This study evaluated the diagnostic value of D-dimer, CRP, and leucocytes count to detect an underlying pulmonary embolism (PE) in patients with pneumonia." (PMID 27313336, 2016). "Meanwhile, three AEs (i.e., chills, pneumonia, and CRP level increased) were found to be commonly associated with the two vaccine types." (PMID 27749923, 2016). "Univariate and multivariate regression analysis determined CRP as the only independent variable significantly associated with CXR-confirmed pneumonia, with CRP-levels >80mg/l corresponding to an OR of 5.9 (CI: (2.4–14.3), p<0.001)." (PMID 26821179, 2016).
pneumonia (continued). "The ROC analysis showed that hs-CRP values were significantly associated with pneumonia (AUC 0.76, 95 % CI 0.72–0.79, age- and sex-adjusted p < 0.0001)." (PMID 26772604, 2016). "In spite of this, nearly all studies that compared procalcitonin and CRP in pneumonia concluded that the latter exhibits a diagnostic performance that is comparable to, if not better than, that of procalcitonin." (PMID 26772604, 2016). "D-dimer performs moderately but significantly better than CRP and leucocytes count in order to predict an underlying PE in patients with pneumonia." (PMID 27313336, 2016). "Regression analysis determined C-reactive Protein (CRP) as the only independent variable significantly associated with CXR-confirmed pneumonia." (PMID 26821179, 2016). "Univariate (model 1) and multivariate (model 2) Cox regression models were then built to test the association of hs-CRP values, dichotomized according to the ROC method, with pneumonia diagnosis." (PMID 26772604, 2016). "The HR values of deaths from pneumonia, sudden deaths, and cancer deaths were also almost linearly associated with CRP." (PMID 26218286, 2015). "Pneumonia is associated with elevated serum CRP levels greater than 10 mg/L, whereas severe pneumonia has serum CRP typically greater than 100 mg/L." (PMID 26672961, 2015). "The amount of CRP in the serum and plasma of patients with pneumonia caused by Klebsiella species had a mean value of 112.9 mg/L ± 116.3 mg/L." (PMID 25674753, 2015). "The amount of C-reactive protein in the serum and plasma of patients with pneumonia caused by E coli had a mean value of 89.9 ± 91.7 mg/L." (PMID 26107669, 2015). "Although this is one limitation of our study, the high CRP concentrations were associated with mortality from other PD-related events, such as pneumonia." (PMID 26218286, 2015). "The levels of CRP were elevated in the plasma of patients with pneumonia caused by MDR P. aeruginosa in the present study." (PMID 26430738, 2015). "Although the strong association between CRP value and the presence of pneumonia is well documented, evidence showing that the test can be used by GPs to improve rational use of antibiotics in LRTI is still sparse and uncertain." (PMID 24886066, 2014). "By contrast, our patient presented mainly with pneumonias, and similar to other C3-deficient patients, he showed high levels of CRP and had episodes of fever, with infectious episodes persisting throughout adolescence." (PMID 22996269, 2013). "The greater than 65 y group had the highest rate of underlying diseases and higher admission rate, pneumonia rate, total duration of fever, and CRP and ESR values than other age groups." (PMID 22443897, 2012). "In this study, we found that clinical parameters such as admission rate, the frequency of underlying diseases, the rate of pneumonia and the values of laboratory parameter, such as CRP and ESR were associated with the increasing age." (PMID 22443897, 2012). "The rates of admission and pneumonia, total duration of fever, the frequency of underlying diseases, and the values of C-reactive protein and erythrocyte sedimentation rate tended to increase as age increased; highest rates were found in the ≥ 65 y group." (PMID 22443897, 2012). "This PCT-threshold was more sensitive and specific than CRP, IL-6, or white blood cell count for differentiating bacterial and viral causes of pneumonia." (PMID 21385367, 2011). "Procalcitonin (PCT) and C-reactive protein (CRP) are used in developed countries to differentiate between viral and bacterial causes of pneumonia." (PMID 20976241, 2010). "How P. falciparum parasites increase PCT and CRP levels independently of the pathogen associated to pneumonia should be considered in the application of these markers for clinical and/or epidemiological purposes." (PMID 20976241, 2010).
pneumonia (continued). "Procalcitonin and soluble triggering receptor expressed on myeloid cells-1 have emerged as reliable diagnostic markers in pneumonia, and are better when compared to other markers, namely, C-reactive protein, leukocyte count, and proinflammatory cytokines." (PMID 20011658, 2009). "The highest values for TNF-α and CRP levels were observed in patients with pneumonia caused by Streptococcus pneumoniae and Legionella pneumophila." (PMID 16899118, 2006). "Our study of 76 patients with probable SARS with pneumonia demonstrated a high case-fatality rate (19.7%), especially in patients with major underlying diseases and high initial CRP levels." (PMID 15200814, 2004). "Routine evaluation of clinical and biochemical markers, including SOFA and Acute Physiology and Chronic Health Evaluation II (APACHE II) scores, pneumonia, and C-reactive protein (CRP) levels, may aid in early risk stratification." (PMID 41658597, 2026). "Cases of severe community-acquired pneumonia had radiographically confirmed pneumonia (consolidated or with pleural effusion) or pneumonia with “other infiltrate” associated with CRP ≥ 40 mg/L with severity criteria according to the 2013 World Health Organization definition." (PMID 40318700, 2025). "Additionally, CRP is obviously useful in dogs with IR, as it can indicate pneumonia, and dogs with IR are suggested to be predisposed to secondary pneumonia." (PMID 40260215, 2025). "Some pediatric HMPV-associated pneumonias were characterized by lobar or segmental consolidation in CT and the significantly elevated CRP levels, which may mimic Mycoplasma Pneumoniae or bacterial infection." (PMID 40346698, 2025). "Additionally, elevated CRP levels are often associated with systemic conditions, such as pneumonia or urinary tract infections, which can further predispose patients to secondary intracranial infections." (PMID 40529435, 2025). "The study demonstrates a significant association between relatively high ferritin levels and increased pneumonia risk, while lower risk was observed in patients with reduced ferritin—especially among postmenopausal women, individuals with CRP > 10 mg/L, and those aged 18–64." (PMID 41445831, 2025). "Our study demonstrated the association of PLT and CRP with the severity and prognosis of pneumonia." (PMID 39926661, 2025). "Predictive models for arrhythmia risk stratification should be developed using machine learning algorithms incorporating CRP levels, electrolyte disturbances, and clinical severity scores to identify pneumonia patients at the highest risk of new-onset atrial flutter." (PMID 40151738, 2025). "However, in the multivariate logistic regression model, only CRP concentration was identified as an independent risk factor for pneumonia (OR = 1.062; 95% Cl 1.008–1.119; p = 0.023)." (PMID 40969806, 2025). "This study suggested that CRP was an independent risk factor for neonatal severe pneumonia." (PMID 40529154, 2025). "Although its sensitivity is high, it is subject to many interfering factors, and trauma, stress, postoperative and any infectious diseases can cause an increase in CRP, so its specificity is low, and its use to predict the prognosis of severe pneumonia can easily misjudge the disease." (PMID 38699695, 2024). "This suggests that low CRP levels can help in ruling out the risk for developing pneumonia." (PMID 38525743, 2024). "Additionally, even a slightly elevated CRP (≥11 mg/L) was positively associated with a pneumonia diagnosis." (PMID 39314554, 2024). "CRP has been used as an indicator of inflammation, and monitoring changes in CRP has been associated with treatment response when managing dogs with pneumonia." (PMID 38819636, 2024). "Similarly, another study utilized a CRP value of ≥ 40 mg/L as a secondary diagnostic criterion for pneumonia." (PMID 38910264, 2024). "Notably, the colocalization evidence for asthmatic pneumonia (coloc.abf-PPH4 = 0.811) robustly supports its association with CRP." (PMID 39229261, 2024).
pneumonia (continued). "This MR study suggested that the genus Roseburia may help mitigate CRP and GlycA-indicated inflammation, and the family Bifidobacteriaceae may help control CRP levels and pneumonia risk." (PMID 38585702, 2024). "However, we found other markers of inflammation independent of clinical comorbidities associated with long-term pneumonia risk, including routinely-available clinical measures such as CRP, an acute-phase protein synthesized by the liver." (PMID 38105941, 2023). "In elderly patients with hip fractures, preoperative serum CRP values might be elevated due to active infections (e.g., pneumonia, urinary tract infection) or fracture-associated soft-tissue damage." (PMID 37107100, 2023). "Elevated CRP can be an independent diagnostic marker for pneumonia in children with suspected symptomatology, but low concentrations do not rule out the condition; thus, such prompt evaluation of the marker is needed in children with lower respiratory tract infections." (PMID 37873776, 2023). "Pneumonia, decreased lymphocytes, and elevated C-reactive protein are potential high-risk factors for neonates with NEC requiring surgical intervention and may have potential clinical implications for predicting surgical risk." (PMID 37576139, 2023). "Clinically relevant pneumonia can be differentiated from other comparable illnesses using traditional diagnostic criteria including a differential blood count and C-reactive protein (CRP) levels." (PMID 37238914, 2023). "The higher levels of IL-6 and CRP observed in patients with pneumonia compared with the other group may be associated with the release of inflammatory mediators from type 2 pneumocytes as the virus enters cells via the ACE2 receptor and undergoes replication." (PMID 37631910, 2023). "In summary, this study revealed that among ICU ventilated patients with a central venous catheter, who developed CR-AB pneumonia, a higher level of CRP and the use of CVVH treatment were identified as risk factors for nosocomial pneumonia-associated bacteremia." (PMID 37768395, 2023). "Further analysis in the same participants showed that Cu/Zn-ratio might be a stronger risk indicator for pneumonia than serum C-reactive protein." (PMID 35781862, 2022). "Probable mechanism for correlation of hypoxia or low oxygen saturation and increase in inflammatory markers like ferritin and CRP is underlying lung parenchymal inflammation secondary to pneumonia resulting into inflammatory burden and hypoxia go hand in hand in these cases." (PMID 36254195, 2022). "It was found in the studied population that chronic lung disease, liver damage, Roma ethnicity, duration from the last MMR dose, CRP, bilateral pulmonary condensation on X-ray, and elevated procalcitonin were independent risk factors for long hospitalization and the development of pneumonia." (PMID 36145449, 2022). "Furthermore, given that C-reactive protein (CRP) is a major inflammatory marker, we also evaluated the association of serum high sensitivity CRP (hsCRP) with pneumonia risk in the same set of participants to make comparisons." (PMID 35781862, 2022). "Our results showed that CRP is a useful diagnostic tool to predict pneumonia." (PMID 35968461, 2022). "In conclusion, we found that some routinely collected data, such as age, C-reactive protein, and the presence of bilateral infiltrate on chest X-ray, can well differentiate patients presenting with pneumonia into groups with high and low risk of SARS-CoV-2 infection." (PMID 33174170, 2021). "The prospective studies showed that increased CRP levels were associated with progressive abnormalities in patients with SARS related pneumonia and could be predictive of severity and death." (PMID 34447386, 2021). "The high ratio of ferritin/CRP is associated with rapid worsening of pneumonia." (PMID 34631752, 2021).